AR (androgen receptor)
Diseases named in the same sentence as AR in open-access papers (continued):
Sharing a sentence is not in itself a finding about the gene and the disease.
tumor (continued). "The GS significantly modifies AR LI ratios in tumour tissue only (Kruskal-Wallis test: p = 0.007), with a significant increase in GS7 (p = 0.019) and GS8 (p = 0.018) as compared to GS6 (post-hoc test)." (PMID 30254333, 2018). "In premenopausal women, patients with PIK3CA wild-type tumors had lower tumor grade, higher ER expression, and lower AR expression when compared to patients with PIK3CA mutant tumors (P = 0.041, P = 0.025, and P = 0.047, respectively)." (PMID 29707142, 2018). "Even though there is a limitation of animal experiments, we found that fibroblasts had two mechanisms for regulating declines in serum PSA after ADT: 1) maintenance of tumor microvessels and 2) secretion of soluble AR-stimulating factors." (PMID 30567361, 2018). "Androgen receptor (AR) is often expressed in BC and several studies suggest that its role depends on the tumor microenvironment as well as the relative levels of circulating estrogens and androgens." (PMID 30210453, 2018). "AR + /FOXA1 + tumours (42.4%) were more frequently: found in older patients, lobular, of lower nuclear grade, with more frequently PIK3CA mutations; exhibited less frequently BRCA1 promoter methylation, defects of PTEN and PD-L1 expression than others." (PMID 29880907, 2018). "Quantitative real-time polymerase chain reaction (qRT-PCR) analysis on microdissected prostatic tissues confirms that tumor tissues express significant lower AR expression than normal and benign tissues." (PMID 29555975, 2018). "The tumor stroma surrounding cancer cells is enriched in fibroblasts that secrete AR-stimulating factors, vascular endothelial growth factor (VEGF), and transforming growth factor (TGF) β." (PMID 30567361, 2018). "Taken together, findings indicate that AR is required for tumor initiation following Pten deletion in CARNs." (PMID 29334357, 2018). "The median AR expression (% of immunopositive tumor cells in the nucleus) in Tanzanian BC patients was 30 (range 0–100) and in Caucasian population was 80 (range 0–100) (p < 0.0001)." (PMID 29651273, 2018). "Conventional anti-hormonal agents, used for the primary treatment of metastatic PCa, are intended to prevent AR activation and curb tumour cell proliferation." (PMID 29682196, 2018). "A recent study has reported that PPARG controls prostate cell growth and differentiation and is involved in androgen-dependent PCa and CRPC evolution, acting as a tumor suppressor through its interplay with AR." (PMID 29966326, 2018). "Functional enrichment analysis indicated high bone morphogenetic protein (BMP) signaling in metastases with high bone cell activity and low tumor cell AR activity." (PMID 29670000, 2018). "In this work, we want to compare AR expression in these two populations of BC patients in the different tumor subtypes." (PMID 29651273, 2018). "Exposure of LuCaP 136 tumor-bearing mice to ganetespib and biomarker analysis after 24 or 48 hours paralleled the in vitro biomarker changes including decreased AR, p-AKT, and p-RPS6 and increased HSP70." (PMID 30467317, 2018). "Unfortunately, the bioactivity of these AR-inhibitors eventually fails as the tumor escapes through heterogenous mechanisms of acquired resistance." (PMID 29691406, 2018). "We show that combination treatment targeting both AR and β-catenin networks is more effective in suppressing tumor growth than targeting a single network." (PMID 29849951, 2018). "Similar to the tumor cells from Patient 1, a subset of both the normal and tumor-derived CRCs from Patient 2 exhibited nuclear AR staining (green fluorescence), a feature consistent with prostate luminal cells." (PMID 29416764, 2018). "Oral administration of 50 mg/kg Uro-A to Balb/c athymic mice inhibited cell growth of xenograft tumours derived from PC-3 (AR−) and C4-2B (AR+) cells." (PMID 30441778, 2018).
tumor (continued). "NEPC can be induced in vitro in AR+ LNCaP cells in androgen-depleted culture conditions, similarly in vivo, and in patient tumours long-term ADT has increased neuroendocrine differentiation." (PMID 29757368, 2018). "In ER-positive BCs and in a subset of ER-negative BCs in which AR activation inhibits tumor growth, natural and synthetic steroidal androgens have been used for therapeutic purpose." (PMID 30210453, 2018). "NANOG has previously been shown to be involved in tumor progression and castration resistance by binding to the androgen receptor/FoxA1 signaling complex." (PMID 29156833, 2017). "Of note, our previous study also indicated that wedelolactone plays a dominant role in determining the activity of different WCE batches and qualifying the WCE potency of in vivo anti-tumor growth and in vitro anti-AR activity." (PMID 29142311, 2017). "AR tumor expression has been recently suggested to be a favourable prognostic parameter in serous EOCs, especially when co-expressed with PR." (PMID 28467804, 2017). "It has become increasingly clear that continuous activation of the AR in CRPC remains the main driving force of tumor progression and metastasis." (PMID 28077787, 2017). "In contrast to ccRCC, 50% AR-positive tumor cells were detected significantly more frequently (P < 0.001) in papRCCs (19%; 13/69)." (PMID 29108248, 2017). "Some tumours acquire genomic amplifications of the AR gene, which increases their sensitivity to androgens and maintains AR signaling under the low testosterone environment of ADT." (PMID 28264478, 2017). "This tumor type (encompassing basal-like-1 and −2, immunomodulatory, mesenchymal, mesenchymal stem-like, luminal androgen receptor or unspecified) has very high rates of tumor recurrence and poor prognosis compared to other breast cancer subtypes." (PMID 29285221, 2017). "In mice with GU weight < 1 gram, AR expression was significantly increased in hyperplasia versus prostate epithelium of the control and in prostate epithelium and hyperplasia versus tumor of the Pre-Finasteride group." (PMID 28765837, 2017). "Expression of AR-FL was increased as well, but fold increases at the primary tumor to CR and CR to abiraterone-resistant stages were minimal compared to fold increases in ARV7 expression." (PMID 28077788, 2017). "Progression to the CR state is often accompanied by an increase in AR levels and transcriptional activity, suggesting the elevated AR levels in the more refractory tumor cells sensitizes these models to repression at lower androgen doses." (PMID 29210989, 2017). "Such functionally defined luminal progenitors can be transformed by distinct sets of genetic perturbations (i.e., AR+AKT/ERG or c‐MYC+PTEN knockout) to form tumor glands." (PMID 28297567, 2017). "A separate study, using circulating tumor cells (CTCs), examined AR amplification as a resistance mechanism in mCRPC patients treated with abiraterone or enzalutamide, and who had received previous docetaxel treatment." (PMID 28604629, 2017). "In late 2015, we reported a differential role of AR depending on the ER status of the tumor using disease-free survival (DFS) as endpoint in a large population-based observational cohort." (PMID 28643022, 2017). "In mice with GU weight > 1 gram, tumor AR expression was significantly decreased versus prostate epithelium and hyperplasia of the control, Pre-Finasteride, Post-Finasteride, and Post-Dutasteride groups." (PMID 28765837, 2017). "We demonstrated that REIC/Dkk-3 was not only an anti-cancer agent that induces tumour specific apoptosis but also restores AR signalling in both CHP-1 and human androgen-independent prostate cancer PC3 cells." (PMID 28599655, 2017). "Supporting the biologic importance of AR, and its viability as a therapeutic target, preclinical data has shown that AR antagonists (e.g., bicalutamide, enzalutamide) exert an anti-tumor effect in a number of ER-negative breast cancer models." (PMID 28085048, 2017).
tumor (continued). "Several evidences indicate that the ubiquitous nucleoside adenosine, acting through A1, A2A, A2B, and A3 receptor (AR) subtypes, plays crucial roles in tumor development." (PMID 29249971, 2017). "Stromal AR also promotes prostate carcinogenesis, for AR-positive stromal cells stimulate tumor development in tissue recombinant studies involving RWPE-1 cells that lack AR as well as AR-negative BPH-1 prostatic cells." (PMID 29181019, 2017). "Although numerous studies on AR have been published, the exact role of AR as tumour-promoting or anti-tumorigenic remains undecided." (PMID 28415597, 2017). "Recurrent disease post-androgen ablation therapy is often characterized by persistent tumor growth in a low testosterone environment with cells expressing varied levels of functional androgen receptor (AR)." (PMID 28212321, 2017). "Recent studies have included PTEN, ERG and AR gene status and mRNA profiling in single circulating tumor cells." (PMID 29069718, 2017). "AR expression was selectively down-regulated when tumor cells were treated with both pulsed physiological or supraphysiological T concentrations." (PMID 29371946, 2017). "In vitro and in vivo studies targeting AR with either AR-siRNA or ASC-J9 (an AR protein degrader) resulted in decreased tumor growth." (PMID 28085048, 2017). "In primary PC, the inhibition of the AR pathway by anti-androgens leads to dramatic tumor regression." (PMID 28511652, 2017). "PC is driven by the androgen receptor (AR) and tumours will initially respond to androgen deprivation therapy (ADT)." (PMID 27903893, 2017). "Tumor size (P=0.002), node status (P<0.001), stage (P<0.001), vascular invasion (P<0.001), AR (P=0.019), radiotherapy (P<0.001) were also predictors of OS." (PMID 28915596, 2017). "In support of this, AR gene amplification and corresponding increase in expression at the protein level has been shown in castrate-resistant tumour samples when compared to matched hormone sensitive samples from the same patient." (PMID 27902483, 2017). "Recent clinical trials have focused around platinum agents and PARP inhibitors (particularly in BRCA1 associated TNBC), androgen receptor antagonists (LAR TNBC) and immune checkpoint inhibitors (TNBCs with high levels of tumor infiltrating lymphocytes)." (PMID 29113326, 2017). "p21cip1 is known to have anti-apoptotic and tumor promoting functions, and in the LNCaP 104R model AR was shown to prime cells for apoptosis via down-regulation of basal p21cip1 expression." (PMID 29210989, 2017). "Immunohistochemical staining of tumor sections verified that AR levels are on average higher in the shTRX1 vs. shLuc tumors and do not correlate well with Ki67 staining, which is higher in the shLuc tumors." (PMID 29089489, 2017). "We conducted exploratory analyses by tumor AR status (AR+ and AR+/ER+/PR+); data were available for 41% of cases." (PMID 28720108, 2017). "Our findings, as presented here, indicate a benefit in TNBC outcomes by inhibiting IGF2 activity using targeted therapies against IGF1R/IR and AR to prevent tumor growth and potentially metastasis." (PMID 29099049, 2017). "OCP on cfDNA confirmed high level EGFR amplification in UMUC-5, and high level AR amplifications in VCaP and 23 of 23 (100%) high tumor content mCRPC samples." (PMID 29163793, 2017). "To understand the genomic profiles of various types of CTCs, we sequenced CTCs from patient 11 (AR+/HR+/HER2- in tumor tissue and AR+/ER+ in CTCs)." (PMID 28957377, 2017). "Another mechanism for increased AR signaling activity is the endogenous expression of androgen synthetic enzymes by tumor tissues, which leads to de novo androgen synthesis or conversion of weaker adrenal androgens into testosterone and DHT." (PMID 28134791, 2017). "This interplay was further elucidated by Naderi and Hughes-Davies, who showed in the cell lines MDA-MB-453 and MDA-MB-361, and in fresh tumor samples, that there is cross-regulation of certain genes between AR and HER2." (PMID 28245550, 2017).
tumor (continued). "There was a significant decrease in AR expression in tumor versus prostate epithelium and hyperplasia of 20-week-old mice." (PMID 28493878, 2017). "Even still, the continued use of hormone-based therapy only adds a few months of life and tumor growth despite AR blockade is frequently observed." (PMID 28212321, 2017). "Activated GR is then able to bind to nuclear AREs and regulate a subset of AR target genes that promote cell survival and tumor progression." (PMID 28604629, 2017). "Mechanistically, TOP2A cooperated with AR to facilitate transcription of androgen responsive genes to promote tumor cell growth." (PMID 29152153, 2017). "In vitro siRNA studies have found that AR knockdown can lead to decreased tumor cell proliferation and increased apoptosis, possibly mediated through AR’s effect on cyclin D1, Bcl-x(L) and MMP-9 gene expression." (PMID 28085048, 2017). "In vitro and animal studies have suggested that dieldrin, DDT, endosulfan, HCH, and toxaphene have the potential to elicit tumor promoting effects mediated through the induction of ER, androgen receptor and aromatase activities." (PMID 28874165, 2017). "Especially, WHO IV tumor tissues showed a remarkable level of AR expression but were nearly undetectable in NC." (PMID 28423563, 2017). "Although two patients were classified as intrinsically resistant by clinical parameters, paired analysis demonstrated clinically relevant alterations in AR and cell-cycle genes only in the resistant tumor." (PMID 32913968, 2017). "In the prostate, SRC-2 amplification coactivates androgen receptor-mediated gene transcription to promote prostate lipogenesis, tumor progression, and metastasis." (PMID 28273073, 2017). "As the analysis of each phosphorylated residue can give discordant results depending on cellular context or tumor microenvironment, we evaluated the total AR phosphorylation status using the Phos-tag SDS-PAGE technique." (PMID 29216878, 2017). "This review summarizes and discusses the available data, suggesting the involvement of androgens and/or the androgen receptor pathways in urothelial carcinogenesis as well as tumor growth." (PMID 28241422, 2017). "The proportion of the PR-ER+AR- subgroup, which exhibited the worst prognosis, was higher in recurrent than primary tumor specimens." (PMID 28416763, 2017). "Ongoing clinical trials evaluating AR antagonists (such as bicalutamide and enzalutamide) in AR+ (defined as nuclear staining in ≥10% of tumor cells by IHC) triple-negative breast carcinomas show promising results." (PMID 29276709, 2017). "Previously, we showed that wedelolactone, apigenin and luteolin are highly enriched in the ethanolic extract of Wedelia chinensis and exhibit anti-tumor function by inhibiting AR activity and clonogenic growth in PCa cells." (PMID 29066975, 2017). "Subsequently, the expression level was suppressed in line with AR overexpression once LuCaP 35CR tumor was established." (PMID 28886115, 2017). "Consistent with our previous observation, in the present study loss of ID4 enhanced in vivo tumor growth in the castration‐resistant environment, more importantly through FKBP52‐mediated AR signaling pathway." (PMID 28252832, 2017). "Using the LAPC-4 (AR+) xenograft model, we succeeded in stimulating tumor growth in castrated mice by using 4-dione, the precursor of androgen T, but the inhibitor RM-532-105 did not reduce their growth." (PMID 28182747, 2017). "Our result also reveals that AR antagonist Enzalutamide has efficacy in reducing HER2 + tumor growth in preclinical models." (PMID 29109513, 2017).
tumor (continued). "AR was mostly increased in prostate epithelium versus tumor in treatment groups, which is similar to the significant increase in AR levels in benign versus tumor in human prostate following finasteride treatment." (PMID 28765837, 2017). "Specifically, activated JNK1 promoted AR nuclear shuttling, concomitant ligand-independent AR transcription and subsequent survivin-regulated tumor growth." (PMID 29152153, 2017). "Using AR immunohistochemistry of cytoblocks we were able to identify Caki2 cells as AR espressing cell lines with over 80% of the tumor cells expressing the receptor." (PMID 29108248, 2017). "This in turn augments AR transcriptional activity and cell proliferation, signaling the reentry of quiescent tumor cells into active cell cycles." (PMID 29066975, 2017). "AR expression in hyperplasia versus prostate epithelium and tumor was significantly increased in the Pre-Dutasteride group with GU weight < 1 gram." (PMID 28765837, 2017). "AR or ERβ expression was also found to correlate with tumor recurrence or progression, respectively." (PMID 28362839, 2017). "Stromal AR activity is also required for tumour formation in prostatic epithelia in recombinant mouse models." (PMID 28117763, 2017). "There was a significant increase in AR expression in hyperplasia compared to prostate epithelium and tumor of 16-week-old mice." (PMID 28493878, 2017). "A variety of experimentally validated target genes regulated by hsa-miR-31-5p has been described in different tumor types, including AR and DNMT3A genes." (PMID 28122331, 2017). "In early stage disease however, it appears as if the stromal AR is required in both tumour initiation and conversely as an inhibitor of progression and metastasis, and unlike its epithelial counterpart holds prognostic information." (PMID 28117763, 2017). "Here, we set out to investigate the role of AR in different prostate epithelial cell lineages in the context of adult prostate homeostasis, androgen-mediated prostate regression–regeneration and tumour initiation." (PMID 28112153, 2017). "After adjustments for age and tumor characteristics (model 1, 0–5 years), there was moderate evidence that patients with AR+ER− tumors had higher BCM during the short-term follow-up compared to patients with AR+ER+ tumors." (PMID 28643022, 2017). "The proportion of ccRCCs positive (defined as more than 5% AR-positive cells) for AR by immunohistochemistry decreased with higher tumor stage (P = 0.001) and presence of distant metastasis (P = 0.013)." (PMID 29108248, 2017). "For ERα, PR and HER2 this is in line with previous findings in solid distant metastases, but AR conversion in late stages of tumor progression is a new observation." (PMID 28903441, 2017). "Our data reveal distinct cell-type-specific roles of epithelial AR in orchestrating prostate homeostasis, and question the notion that epithelial AR serves as a tumour suppressor in early cancer initiation." (PMID 28112153, 2017). "The expression of AR was measured by immunohistochemistry and assessed by digital image analysis using a tissue microarray containing tumor tissue of a large and well-documented series of RCC patients with long-term follow-up information." (PMID 29108248, 2017). "In this article, we provide an overview of the evidence supporting the use of AR-directed therapies in prostate as well as other cancers, with an emphasis on the rationale for targeting AR-signaling across tumor types." (PMID 28085048, 2017). "AR positivity in tumors was strongly correlated with gender (male vs. female: OR = 0.658; P = 0.027) or tumor grade (low-grade vs. high-grade: OR = 0.575; P<0.001)." (PMID 28362839, 2017). "Patients with immunohistochemically AR(-)/FOXA1(-) tumor frequently showed node metastasis, high grade, and high Ki-67 proliferation, therefore, significantly worse survival in ER-positive disease." (PMID 29137314, 2017).